B3GALT9 (beta-1,3-galactosyltransferase 9)
Description:
Putative glycosyltransferase that could catalyze the transfer of galactose residues from UDP-alpha-D-galactose.
Synonyms: B3GNT10
Tractability: Antibody: UniProt predicts a signal peptide or a membrane-spanning region.
Gene: Protein-coding gene on chromosome 9 (120,792,403 to 120,801,787, forward strand). Ensembl gene ENSG00000214654.
Subcellular location: Golgi apparatus membrane
Gene Ontology:
Molecular function: hexosyltransferase activity
Biological process: carbohydrate derivative metabolic process; glycoprotein biosynthetic process
Cellular component: Golgi membrane; membrane
Homologues: Orthologues: chimpanzee B3GALT9 (98% identical), macaque B3GALT9 (94% identical), rabbit B3GALT9 (85% identical), guinea pig B3GALT9 (81% identical), mouse B3galt9 (79% identical), rat B3galt9 (77% identical), tropical clawed frog b3galt9 (53% identical), zebrafish b3galt9 (40% identical), Drosophila melanogaster brn (23% identical), Caenorhabditis elegans bre-5 (21% identical), Caenorhabditis elegans F21C10.3 (10% identical), Caenorhabditis elegans B0024.3 (9% identical). Paralogues in human: B3GALT4 (28% identical), B3GNT5 (28% identical), B3GNT4 (24% identical), B3GNT6 (23% identical), B3GALT5 (22% identical), B3GNT3 (22% identical), B3GALT2 (22% identical), B3GNT7 (22% identical), B3GNT8 (22% identical), B3GALT1 (22% identical), B3GNT2 (22% identical), B3GNT9 (22% identical), and 3 more.